CDK2AP2 (cyclin dependent kinase 2 associated protein 2)
Description:
Acts as a component of the histone deacetylase NuRD complex which participates in the remodeling of chromatin. Inhibits cell cycle G1/S phase transition by repressing CDK2 expression and activation; represses CDK2 activation by inhibiting its interaction with cyclin E and A. Plays a role in regulating the self-renewal of embryonic stem cells (ESCs) and in maintaining cell survival during terminal differentiation of ESCs (By similarity). Regulates microtubule organization of metaphase II oocytes (By similarity).
Synonyms: DOC-1R; DOC1R; p14
Tractability: PROTAC: ubiquitination databases record sites on it.
Gene: Protein-coding gene on chromosome 11 (67,506,490 to 67,508,701, reverse strand). Ensembl gene ENSG00000167797.
Subcellular location: Cytoplasm; Nucleus
Subcellular location (Human Protein Atlas): Nucleoplasm
Pathways (Reactome):
Chromatin organization: Interaction of NuRD complexes with transcription factors; NuRD complex assembly
Gene Ontology:
Molecular function: protein binding
Biological process: negative regulation of G1/S transition of mitotic cell cycle; regulation of microtubule cytoskeleton organization; regulation of stem cell division
Cellular component: cytoplasm; nucleus; NuRD complex; microtubule; nucleoplasm
Genetic constraint (gnomAD): Loss-of-function variants: 1 observed, 11.56 expected, observed/expected ratio (o/e) 0.0865, 90% interval 0.03 to 0.41. The upper end of that interval is the gene's LOEUF score, 0.41, which puts it in group 1 of 6, group 1 being the genes least tolerant of losing a copy. Missense variants: 129 observed, 153.79 expected, observed/expected ratio (o/e) 0.84, 90% interval 0.73 to 0.97. Synonymous variants: 76 observed, 66.53 expected, observed/expected ratio (o/e) 1.14, 90% interval 0.95 to 1.38.
Homologues: Orthologues: chimpanzee CDK2AP2 (100% identical), macaque CDK2AP2 (99% identical), pig CDK2AP2 (99% identical), guinea pig CDK2AP2 (98% identical), mouse Cdk2ap2 (98% identical), rat Cdk2ap2 (84% identical), tropical clawed frog cdk2ap2 (68% identical), zebrafish cdk2ap2 (67% identical), Drosophila melanogaster CDK2AP1 (45% identical), Caenorhabditis elegans Y43F4B.10 (25% identical). Paralogues in human: CDK2AP1 (58% identical).
Diseases named in the same sentence as CDK2AP2 in open-access papers:
CDK2AP2 is named in the same sentence as 9 diseases in open-access papers, as found by Europe PMC text mining. Sharing a sentence is not in itself a finding about the gene and the disease. The quoted sentences say what the papers report.
gastric cancer (1 paper, 2013). A primary or metastatic malignant neoplasm involving the stomach. "In gastric cancer, a large number of genes (e.g., CDKN2A, CDK2AP2, CDH1, MGMT, RASSF1, RUNX3, and DLC1) have been shown to be suppressed by CpG island hypermethylation." (PMID 23179365, 2013).
glioblastoma (1 paper, 2018). The most malignant astrocytic tumor (WHO grade IV). "The qRT-PCR results confirmed the down-regulation of the mitotic cell cycle regulators such as CDK2 and SMC4 in both lung and glioblastoma SOX2OT knocked down cancer cell lines, while the CDK2AP2 which is also known to interact and inhibit CDK2, is up-regulated more than two times in treated cells." (PMID 30202240, 2018).
ovarian carcinoma (1 paper, 2025). A malignant neoplasm originating from the surface ovarian epithelium. "We found that the expression of BANF1, CDK2AP2, DDT, LRIG1, MRPL4, and S100A13 was upregulated in ovarian cancer samples, and the expression of EPS8, NUCB2, PAF1, PMP22, RABGAP1L, and USO1 was upregulated in normal samples." (PMID 41000388, 2025).
pterygium (1 paper, 2012). A wedge-shaped fibrovascular lesion arising from the bulbar conjunctiva and extending to the cornea.
cancer (1 paper, 2018). A tumor composed of atypical neoplastic, often pleomorphic cells that invade other tissues. "Particularly, the cell cycle and mitotic regulatory genes expression including: CDK2, CDK2AP2, ACTR3, and chromosome structure associated genes like SMC4, INCENP and GNL3L are changed in treated cancer cells." (PMID 30202240, 2018).
tumor (1 paper, 2025). "The analysis revealed that in the training set, the expression of BANF1, CDK2AP2, DDT, LRIG1, MRPL4, and S100A13 was significantly upregulated in tumor samples, and the expression of EPS8, NUCB2, PAF1, PMP22, RABGAP1L, and USO1 was higher in control samples (p < 0.05)." (PMID 41000388, 2025).
CDK2AP2 also shares sentences with these, for which no sentence is quoted: and Muscular Disorder (1 paper); Fever (1); infection (1).